BEST1 (bestrophin 1)
Diseases named in the same sentence as BEST1 in open-access papers (continued):
Sharing a sentence is not in itself a finding about the gene and the disease.
Best vitelliform macular dystrophy (continued). "Genetic analysis of the proband detected two sequence variants of the BEST1 gene in the heterozygous state: a novel variant c.717delG, p.V239VfsX2 and an already described c.763C>T, p.R255W variant associated with Best vitelliform macular dystrophy and ARB." (PMID 27071392, 2016). "The first disease shown to be caused by BEST1 sequence variants was Best vitelliform macular dystrophy (BVMD), a retinal disease characterized by bilateral yellowish yolk-colored lesion in the macula." (PMID 27071392, 2016). "The purpose of the current study was to investigate the 11 bestrophin-1 (BEST1) exons in patients with best vitelliform macular dystrophy (BVMD), and to characterize the associated clinical features." (PMID 25936525, 2015). "Best vitelliform macular dystrophy was the first inherited retinal condition in which mutations in the BEST1 gene were shown to be the underlying cause." (PMID 23710333, 2013). "The first disease shown to be caused by BEST1 sequence variants was Best vitelliform macular dystrophy (BVMD), a retinal disease characterized by a bilateral yellowish yolk-like lesion in the macula." (PMID 22162627, 2011). "In 1998, the gene VMD2, which encodes for the human bestrophin-1 (hBest1) protein, was found to be responsible for the inherited Best vitelliform macular dystrophy." (PMID 19262692, 2009). "Additionally, mutations in the BEST1 gene are associated with Best disease, affecting retinal pigment epithelial cells and resulting in vision loss." (PMID 39439625, 2024). "Because of this, some hypothesize that AOFVD patients with certain BEST1 mutations may actually possess a mild version of Best disease with later onset." (PMID 38983024, 2023). "Best vitelliform macular dystrophy (Best disease, BD) is an autosomal dominant, early‐onset macular dystrophy frequently caused by mutations in the bestrophin (BEST1) gene, with over 200 missense mutations in BEST1 already identified." (PMID 35739648, 2022). "In addition, mutations in BEST1 were identified in one pedigree in the cohort, leading to a rediagnosis of Best Vitelliform Macular Dystrophy." (PMID 27624628, 2016). "For instance, pathogenic BEST1 variants are associated with central visual acuity impairment, leading to Best vitelliform macular dystrophy (BVMD)." (PMID 41440982, 2025). "The most common mutations in BEST1 is related to Best vitelliform macular dystrophy (BVMD, OMIM: 153700), which is also known as Best disease." (PMID 36835965, 2023). "Best Vitelliform Macular dystrophy (BVMD) is the most prevalent of the distinctive retinal dystrophies caused by mutations in the BEST1 gene." (PMID 35806438, 2022). "Approximately 10% of the Best vitelliform macular dystrophy (BVMD) patients with BEST1 mutations had normal vision and asymptomatic." (PMID 32967234, 2020). "BEST1 mutations are classically associated with Best vitelliform macular dystrophy (BVMD), a disease restricted to the macula." (PMID 29862063, 2018). "Mutations in the gene for Best1 are leading to best vitelliform macular dystrophy (BVMD) and are found in several other types of maculopathy." (PMID 26019622, 2015). "Only one BEST1 mutation was located within one of the four mutational clusters described in typical autosomal dominant Best vitelliform macular dystrophy (BVMD)." (PMID 22162627, 2011). "In contrast, BEST1 variants primarily affect the retinal pigment epithelium (RPE), leading to Best vitelliform macular dystrophy, which typically shows an abnormal electro-oculogram (EOG) without extraocular manifestations." (PMID 41440982, 2025). "There is evidence indicating that BEST1 mutations alters the regulation of VDCC kinetics via bestrophin-1, and this reduces the response to light in electrooculogram (EOG) in patients with Best’s disease." (PMID 39457382, 2024). "It was found that loss of Bestrophin 1 function led to Best vitelliform macular dystrophy (BVMD) in humans, which resulted in the gene being also named the VMD2 gene." (PMID 38279294, 2024).
Best vitelliform macular dystrophy (continued). "Best vitelliform macular dystrophy (BVMD), also known as Best disease, is an autosomal-dominant inherited disorder caused by mutations in BEST1 gene." (PMID 37176614, 2023). "Best vitelliform macular dystrophy (BVMD), whose inheritability was clinically identified in 19051, was the first of the group to be linked to BEST1 mutations." (PMID 35882966, 2022). "A recent study demonstrated a beneficial safety profile and satisfactory efficacy for AAV2-mediated delivery of the BEST1 gene to reverse key ultrastructural and molecular Best disease characteristics in a naturally occurring canine Best disease model." (PMID 34612806, 2021). "Best vitelliform macular dystrophy is an inherited disease of the central retina caused by pathogenic variants in the VMD2 gene, now known as BEST1." (PMID 33154968, 2020). "Bestrophin-1 (BEST1, also known as VMD2) was first identified in Best vitelliform macular dystrophy (BVMD, Best disease), a disease associated with BEST1 mutations." (PMID 28831140, 2017). "The precise mechanism that leads different BEST1 mutations to cause both peripheral retina disease (ADVIRC) and maculopathies, such as Best disease, remains to be determined." (PMID 27653836, 2016). "Increasing expression of genes like BEST1 in Best Vitelliform Macular Dystrophy." (PMID 39439625, 2024). "The BEST1 gene, also known as VMD2, which encodes the Best1 protein in humans, was first identified through genetic linkage experiments associating it with mutations that cause the eye disease Best vitelliform macular dystrophy (BVMD)." (PMID 34612806, 2021). "Bestrophins (Best) were first found by genetic linkage of human Best-1 to a juvenile form of macular degeneration called Best vitelliform macular dystrophy (“Best disease”), and have been proposed to be a regulator of Ca2+-activated Cl− channels in different kinds of cells." (PMID 25329324, 2014). "Best vitelliform macular dystrophy (BVMD, OMIM #153700) is an IRD primarily caused by autosomal dominant variants in the BEST1 gene (OMIM #607854) in 11q12." (PMID 38732293, 2024). "Two additional maculopathies were characterized within 3 consanguineous families with homozygous BEST1 variants, 2 families with autosomal recessive Bestrophinopathy (OMIM:611,809) and one with Best vitelliform macular dystrophy (BVMD) (OMIM:153,700)." (PMID 35551639, 2022). "Best vitelliform macular dystrophy (BVMD, OMIM: 607854) is most commonly inherited in an autosomal dominant manner and caused by mutations in the gene BEST1 (11q13), with over 200 mutations reported up to date." (PMID 34253754, 2021). "Mutations in the Bestrophin 1 gene (BEST1, VMD2) cause several phenotypically distinct monogenic retinal disorders in man, the prototypical one being autosomal dominant Best Vitelliform Macular Dystrophy (BVMD)." (PMID 39774293, 2025). "Best vitelliform macular dystrophy (BVMD), caused by pathogenic variants of the BEST1 gene, has not been reported in association with cataracts and ocular malformations." (PMID 37076855, 2023).
autosomal dominant vitreoretinochoroidopathy (39 papers, 2009 to 2025). Autosomal dominant vitreoretinochoroidopathy (ADVIRC) is a genetic vitreous-retinal disease characterized by ocular developmental anomalies such as microcornea, a shallow anterior chamber, glaucoma and cataract. "Differential diagnoses of reduced EOG light-rise include OTX2-associated retinal dystrophy, and autosomal dominant vitreoretinochoroidopathy (ADVIRC) due to selected bestrophin-1 (BEST1) variants." (PMID 40455352, 2025). "Here we describe a patient with atypical presentation of autosomal dominant vitreoretinochoroidopathy (ADVIRC) with a novel missense mutation in BEST1 gene and briefly review reported ADVIRC-associated genetic mutations." (PMID 36712704, 2022). "The c.704T > C; p.(V235A) BEST1 mutation was previously reported to be mislocalized at least in part to the apical surface of hiPSC-RPEs from an autosomal dominant vitreoretinochoroidopathy patient." (PMID 33154968, 2020). "A subtype of Best disease, autosomal dominant vitreoretinochoroidopathy (ADVIRC) is a chorioretinal degeneration caused by a mutation in the Bestrophin-1 (BEST1) gene, and evidence suggests that EMT of RPE cells plays a role in its pathogenesis." (PMID 32671066, 2020). "One allele of the gene bestrophin 1 (BEST1), [OMIM 607854], is reported to cause dominant vitreoretinochoroidopathy together with nanophthalmos, although the relationship of this phenotype to pure nanophthalmos seems uncertain." (PMID 21850159, 2011). "Autosomal dominant vitreoretinochoroidopathy (ADVIRC or VRCP, OMIM 193220) is a rare macular dystrophy that is an autosomal dominant disorder with mutations on BEST1, and is typically presented in the first decade of life." (PMID 36835965, 2023). "Heterozygous mutations in BEST1, which usually cause typical Best VMD, may also cause adult vitelliform macular degeneration, autosomal dominant bestrophinopathy, and a rare and unique condition called autosomal dominant vitreoretinochoroidopathy." (PMID 20057903, 2009).
adult-onset vitelliform macular dystrophy (24 papers, 2008 to 2025). "Disruptions in the function of Bestrophin-1 causes a range of macular dystrophies, most notably Vitelliform Macular Dystrophy or Best’s disease." (PMID 28687758, 2017). "Vitelliform macular dystrophy (VMD) is an autosomal-dominant disease that can cause a gene mutation of bestrophin-1 (Best-1)." (PMID 22817759, 2012). "Mutations in human bestrophin 1 are associated with at least three autosomal-dominant macular dystrophies including Best disease, adult onset vitelliform macular dystrophy and autosomal dominant vitreo-retinochoroidopathy." (PMID 18307799, 2008). "Of these, vitelliform macular dystrophy is among the most common and is caused by dominant or recessive mutations in the BEST1 gene encoding a protein postulated to play a number of roles, including functioning as a Ca2+-dependent Cl− channel associated with basolateral plasmalemma of the RPE." (PMID 24599007, 2014). "Subtypes of BEST1-3 are responsible for vitelliform macular dystrophy, regulating the cilia of olfactory sensory neuronal activity; others regulate cGMP-dependent calcium-activated chloride conductance in vascular smooth muscle cells." (PMID 39699952, 2024). "Adult-onset vitelliform macular dystrophy (AVMD) is a common and benign macular degeneration which can be caused by BEST1 mutation." (PMID 28831140, 2017). "In humans, Bestrophin 1 is mutant in vitelliform macular dystrophy (Best’s disease)." (PMID 23056495, 2012).
retinal dystrophies (22 papers, 2010 to 2025). "It is an inherited retinal dystrophy (IRD) associated with biallelic variants in the bestrophin-1 gene (BEST1, OMIM *607,854)." (PMID 39048936, 2024). "Variants in BEST1 are a well-described cause of inherited retinal dystrophy, with a continually expanding variety of phenotypes." (PMID 36264634, 2022). "Of all inherited retinal dystrophies, variants in BEST1 seem to be associated most with unilateral or asymmetric disease." (PMID 33039401, 2021). "The locus included the VMD2/BEST1 gene previously implicated in nanophthalmos that encodes a calcium-activated chloride channel associated with nanophthalmos and four types of retinal dystrophy." (PMID 31048900, 2019). "Five Italian patients from four independent pedigrees with retinal dystrophy associated with biallelic BEST1 variants were recruited from different parts of Italy." (PMID 22162627, 2011). "Since the first description of ARB as a novel retinal dystrophy caused by bialleic mutations in BEST1, our understanding of the clinical presentation and pathophysiology of the condition has progressed." (PMID 21203346, 2010). "ARB is a distinct type of retinal dystrophy caused by biallelic BEST1 gene variants." (PMID 40414863, 2025). "USH2A was the most frequent gene associated with RP, RDH12 early-onset severe retinal dystrophy, ABCA4 Stargardt disease, PROM1 cone-rod dystrophy, and BEST1 macular dystrophy." (PMID 37217489, 2023). "Lapponian herders (LHs) are affected with several types of inherited retinal dystrophies, and variants in PRCD and BEST1 genes have been associated with generalized PRA and canine multifocal retinopathy 3 (cmr3), respectively." (PMID 33606121, 2021). "Genetic etiologies of retinal dystrophy causing both autosomal dominant and recessive disease have been described in the literature and include RHO, RP1, BEST1, GUCY2D, RAX2, and RPE65." (PMID 31856884, 2019). "CTNNA1-associated retinal dystrophy also lacks ADVIRC-associated features such as microcornea, shallow anterior chamber, iris dysgenesis, macular oedema, optic nerve dysplasia, progressive generalised atrophy and severe ERG abnormalities distinguishing it from BEST1-related ADVIRC." (PMID 40455352, 2025). "BEST1 mutations may also be associated with several other eye diseases, including adult-onset vitelliform macular dystrophy (AOVMD), autosomal dominant vitreo-retinochoroidopathy (ADVIRC), retinitis pigmentosa, and microcornea, retinal dystrophy, cataract, and posterior staphyloma (MRCS) syndrome." (PMID 22162627, 2011). "A third genetic form of inherited retinopathy is suspected in LH, as not all cases of inherited retinal dystrophies have been explained by the known PRCD and BEST1 variants." (PMID 33606121, 2021).
retinitis pigmentosa (20 papers, 2010 to 2025). Retinitis pigmentosa (RP) is an inherited retinal dystrophy leading to progressive loss of the photoreceptors and retinal pigment epithelium and resulting in blindness usually after several decades. "Several of these genes were established RPE markers such as RPE65 and BEST1, mutations in both of which can cause retinitis pigmentosa and other retinopathies." (PMID 34200671, 2021). "For example, BEST1 gene mutations result in a spectrum of ocular phenotype such as microcornea, cataract, retinitis pigmentosa, and macular and rod-cone dystrophy." (PMID 32967234, 2020). "Retinitis pigmentosa can be caused by mutation of the corresponding I205 residue of human BEST1 to threonine." (PMID 30628889, 2019). "Association of BEST1 missense mutations with the human PRA equivalent Retinitis Pigmentosa has recently been established." (PMID 21197113, 2010). "Effect of combinations of Txnip.C247S with Best1-Nrf2 or Tgfb1 on retinitis pigmentosa cone survival." (PMID 33847261, 2021). "Pathogenic variations in the BEST1 gene have been shown to be associated with age-related macular degeneration, BVMD, retinitis pigmentosa, and vitreoretino-choroidopathy [Genetics Home Reference]." (PMID 34209753, 2021). "A BEST1 homozygous change was reported in four patients of the same family of Pakistani origin; their phenotype was interpreted as retinitis pigmentosa even though it showed some clinical similarities with the ARB phenotype." (PMID 22162627, 2011). "Mutations in BEST1 cause several phenotypes including autosomal dominant (AD) Best vitelliform macular dystrophy type 2 (BVMD), AD vitreo-retino-choroidopathy (ADVIRC), and retinitis pigmentosa-50 (RP50)." (PMID 31766397, 2019). "Vessel density was found to be highest in EFEMP1, BEST1, TIMP3, RS1, and PRPH2 (11.0%, 10.4%, 10.1%, 10.1%, 9.2%) and was lower in retinitis pigmentosa (RP) and Leber congenital amaurosis genes." (PMID 39896422, 2025). "Effect of dominant negative HIF1α and Best1-Txnip.C247S.LL351 and 352AA on retinitis pigmentosa cone survival." (PMID 33847261, 2021).
macular dystrophies (16 papers, 2013 to 2025). "Autosomal dominant Best vitelliform macular dystrophy (BVMD, also called Best disease), caused by variants in the BEST1 gene, is one of the most common inherited macular dystrophies." (PMID 40327408, 2025). "Autosomal dominant Best vitelliform macular dystrophy (BVMD), caused by variants in the BEST1 gene, is one of the most common inherited macular dystrophies." (PMID 40327408, 2025). "We searched the electronic patient records of our large inherited retinal disease cohort, quantifying numbers of males and females with the more common (non-ABCA4) inherited macular dystrophies (associated with BEST1, EFEMP1, PROM1, PRPH2, RP1L1, and TIMP3)." (PMID 38700873, 2024). "We also prioritized two VUS in BEST1 gene that affect two cases with Macular Dystrophy; VUS NM_004183.3: c.828C > G, reported as pathogenic in VarSome, and, VUS NM_001139443.1: c.671A > G with other described pathogenic variants in the same amino acid." (PMID 33623043, 2021). "Mutations in BEST1 gene, encoding the bestrophin-1 (Best1) protein are associated with macular dystrophies." (PMID 23880862, 2013). "In addition, after reviewing previously published papers, it appears that mutations in BEST1 can cause a broad clinical spectrum of macular dystrophies, which suggests a multifunctional role of the protein in the retina." (PMID 38411968, 2024). "For macular dystrophies, the most common gene by far was ABCA4 (autosomal recessive), whereas PRPH2 and BEST1 were implicated frequently in autosomal dominantly inherited macular dystrophies." (PMID 32423767, 2020). "Significant sex imbalances have been observed in certain autosomally-inherited macular dystrophies (such as those associated with ABCA4, BEST1 and EFEMP1), although the underlying mechanisms remain unclear." (PMID 39632990, 2025).
retinal disease (16 papers, 2010 to 2026). "Variants in ABCA4, PRPH2, and BEST1 alone explained retinal disease in 60.7% of the MD cohort, similar to previously published results (57%)." (PMID 33546218, 2021). "A homozygous variation in the BEST1 gene was detected in the 256 gene coding regions associated with retinal diseases in the peripheral blood of the subjects." (PMID 31969119, 2020). "Mutations in ABCA4, PRPH2 and BEST1 were predominant, explaining the retinal disease in 57% of the entire cohort and 74% of the solved cases." (PMID 29555955, 2018). "Because the affected dogs did not share common alleles, we excluded single, fully penetrant mutations in six known canine retinal disease genes: BEST1, PDE6B and PDE6A, RPE65, NPHP4, and CNGB3." (PMID 25198798, 2014). "Because of this phenotypic heterogeneity, BEST1 mutations may be involved in retinal diseases other than those already identified." (PMID 22162627, 2011). "In 57% of all MD/CCRD cases (77% of the 185 solved cases), retinal disease was explained by mutations in ABCA4 (n = 94, 37%), PRPH2 (n = 29, 12%) or BEST1 (n = 19, 8%; including 5 a.r. and 14 a.d. mutations)." (PMID 29555955, 2018). "Inherited retinal disease can also result from a primary dysfunction of the retinal pigment epithelium (RPE) of which RPE65- or BEST1-mutant dogs are examples." (PMID 25198798, 2014). "known retinal disease genes (BEST1 [NM_004183], C1QTNF5 [NM_015645], CDH3 [NM_001793], LRAT [NM_004744], RDH5 [NM_002905], RDH11 [NM_016026], RGR [NM_002921], RLBP1 [NM_000326] and STRA6 [NM_022369])." (PMID 20479888, 2010). "Similarly, recurrence risk was complicated in Patient 6 who was found to have in addition to the primary finding of EPCAM-related tufting enteropathy the unexpected finding of BEST1-related inherited retinal disease." (PMID 38716412, 2024). "In strong support of this finding, imbalanced transcription of the two endogenous BEST1 alleles was detected in donor-derived iPSC-RPE and native RPE cells, consistent with the previous observation that BEST1 is one of the inherited retinal disease genes with AEI in the human retinal transcriptome." (PMID 34061021, 2021). "Among betrophinopathies, ARB is presumed to be a retinal disease with a “null” phenotype for Best1." (PMID 31969119, 2020). "BEST1 variant (NM_001139443.1:c.242G>A) was heterozygous in an individual not known to be affected by retinal disease (allele frequency = 0.38% in our in-house database)." (PMID 27391102, 2016).